PIK3CA (phosphatidylinositol-4,5-bisphosphate 3-kinase catalytic subunit alpha)
Diseases named in the same sentence as PIK3CA in open-access papers (continued):
Sharing a sentence is not in itself a finding about the gene and the disease.
benign tumors (5 papers, 2020 to 2025). "As shown in the mutation profiles, PIK3CA mutations were frequently found in the benign tumors, suggesting that this key driver mutation is commonly acquired in advance of malignant progression." (PMID 32680987, 2020). "This suggests that PIK3CA mutations may play a major role in regulating cell proliferation at an early stage, and that benign tumors may progress to malignancy through additional factors or mutations." (PMID 38033642, 2023). "Alpelisib could be utilized in the treatment of PIK3CA-mutated benign tumors when surgical excision is not feasible owing to factors such as old age or dog owner’s reluctance." (PMID 38033642, 2023). "However, there was no apparent relationship between the occurrence of PIK3CA mutations and malignant or benign tumors." (PMID 38033642, 2023).
gynecological tumors (5 papers, 2020 to 2025).
head and neck tumors (4 papers, 2018 to 2023). "PIK3CA mutations are more frequent in ESCC than in EAC; interestingly, PIK3CA mutations are also frequent in other squamous tumors, such as lung and head and neck tumors." (PMID 36661697, 2023). "Moreover, we evaluated the expression of SOX2 and PIK3CA in the 520 head and neck tumors with RNA sequencing data available from TCGA." (PMID 30108202, 2018).
neurological diseases (3 papers, 2019 to 2025). "This suggests that PIK3CA might have different mechanisms of action in the onset and progression of different neurological diseases." (PMID 38886317, 2025).
blood cancer (2 papers, 2019 to 2025). "However, when ovarian cancer cells were segregated based on their KRAS or PI3K (includes PIK3CA and PTEN mutations) mutational status, FK866-sensitivity (IC50) was more comparable to the most sensitive cell types (highly sensitive blood cancers)." (PMID 41419662, 2025).
inflammation (1 paper, 2023). Aberrant reaction of the microcirculation characterized by movement of fluid and leukocytes from the blood into extravascular tissues. "Interestingly, the own definitive molecular features of EBV-positive GC include PIK3CA mutations, which may be associated with signaling pathways leading to GC oncogenic process by promoting chronic gastric inflammation." (PMID 36744128, 2023).
metabolic disorders (1 paper, 2023). "We suggest that a more diffuse distribution or even constitutional occurrence of PIK3CA variants may shift the phenotype from growth-dominated disorders to primarily metabolic disorders." (PMID 37974153, 2023).
PIK3CA also shares sentences with these, for which no sentence is quoted: diffuse large B-cell lymphoma (8 papers); Parkes-Weber syndrome (6); CNS tumors (5); immune disorders (5); prostate adenocarcinoma (5); adenoid cystic carcinoma (4); brain cancer (4); cerebral cavernous malformation (4); lobular carcinoma (4); mucinous adenocarcinoma (4); polymicrogyria (4); scoliosis (4); skin cancer (4); Smith-Kingsmore syndrome (4); acute lymphoblastic leukemia (3); cervical intraepithelial neoplasia (3); CLAPO syndrome (3); Epstein-Barr virus infection (3); Macrocephaly (3); malignant glioma (3); pancreatic adenocarcinoma (3); peritoneal cancer (3); poorly differentiated thyroid cancer (3); vascular anomaly (3); anaplastic oligodendroglioma (2); B cell lymphoma (2); benign hemangioma (2); Bourneville Disease (2); chronic obstructive pulmonary disease (2); Cirrhosis (2).
A further 186 diseases each share a sentence with PIK3CA in 2 papers or fewer.